TYR (tyrosinase)
Diseases named in the same sentence as TYR in open-access papers (continued):
Sharing a sentence is not in itself a finding about the gene and the disease.
melanoma (continued). "Inhibition of cellular tyrosinase activity and melanin production was also investigated in melanoma B16F10 cells." (PMID 27829416, 2016). "The prooxidant state in melanoma induces alterations in proteins involved in melanogenesis, such as tyrosinase and TYRP1." (PMID 27206673, 2016). "α-Arbutin possesses a 10-fold stronger inhibitory effect on the activity of tyrosinase from human malignant melanoma cells compared to its anomer, whereas β-arbutin reduces tyrosinase activities from mushroom and mouse melanoma." (PMID 27276911, 2016). "The exact mechanisms of melanoma-associated vitiligo development are still under study, but it is clear that CD8+ T cell recognizing autoantigens have a major role and that tyrosinase and gp100 are among these autoantigens." (PMID 25933939, 2015). "Here, we show for the first time that a small library of mimosine dipeptide enantiomers (Mi-l/d-amino acid) inhibit the melanogenesis in B16F10 melanoma cells by down-regulating the cellular tyrosinase with little effect on their growth or viability." (PMID 26287130, 2015). "Of note, miR-203 was highly expressed in Black exosomes, and this miR was recently reported to be a key regulator of melanogenesis in melanoma cells, increasing pigmentation and TYR protein levels." (PMID 26103923, 2015). "Their anti-melanogenic activity is due to intracellular tyrosinase inhibition with little effect on the growth or viability of B16F10 melanoma cells." (PMID 26287130, 2015). "In murine melanoma B16-F10 cells, 4-(phenylsulfanyl)butan-2-one also inhibited the cell-based tyrosinase activity, and decreased the melanin production." (PMID 26343635, 2015). "The anti-melanogenic was assessed in B16F10 melanoma cells by melanin synthesis and intracellular tyrosinase inhibitory activity." (PMID 26389869, 2015). "All extracts showed also the ability to enhance melanogenesis and tyrosinase activity of B16F10 melanoma cells." (PMID 26329604, 2015). "Media rich in tyrosine, such as DMEM, activates the pigmentary system in Ab hamster melanoma cells with an accompanying increase in tyrosinase activity." (PMID 25811927, 2015). "lanyuensis isolated compounds on tyrosinase activity and melanine content formation in melanoma cells." (PMID 26151114, 2015). "Two of them, Mi-d-Trp and Mi-d-Val, turned out to be the most potent inhibitors on melanin content and cellular tyrosinase in B16F10 melanoma cells." (PMID 26287130, 2015). "We selected six melanoma-associated antigens (MAGE-A3, NY-ESO-1, gp100, Mart1, tyrosinase and TRP-2) that are frequently recognized in patients with the aim of identifying novel T-cell epitopes restricted to HLA-A1, -A3, -A11 and -B7." (PMID 25854582, 2015). "Assays of mushroom and cellular tyrosinase activities and melanin content of mouse melanoma cells were performed spectrophotometrically, and the expression of melanogenesis-related proteins was determined by Western blotting." (PMID 25961954, 2015). "We performed an enzyme kinetics study of Fa-a and Fa-b in B16 melanoma cells based tyrosinase assays with various concentrations of the L-DOPA substrate." (PMID 25197307, 2014). "Six compounds isolated from I. obliquus were characterized and evaluated for their tyrosinase inhibitory activity in B16 melanoma cells." (PMID 25197307, 2014). "Incubated for 24 h, CGA (500 μM) improves melanogenesis while suppressing tyrosinase activity in B16 melanoma cells or 8-methoxypsoralen (8-MOP) co-incubated B16 melanoma cells." (PMID 25157464, 2014). "As a continuation of these studies, a new one determined the safety and effectiveness of the murine tyrosinase xenogeneic vaccine for canine digit melanoma when used in conjunction with local and regional disease control." (PMID 25506617, 2014). "We also examined the TYR activity and melanin content in B16 melanoma cells, as well as the expression of TYR, TRP-1, TRP-2 and MITF in B16 cells." (PMID 24884952, 2014).
melanoma (continued). "Tyrosinase is part of the biosynthesis process of melanin and is constitutively expressed in melanocytes and melanoma cells." (PMID 25667918, 2014). "Xenografted tumors displayed expression of CD271 as well as melanoma differentiation markers TYR and MITF." (PMID 24799129, 2014). "Tyrosinase mRNA levels are detectable in the blood of melanoma patients with advanced metastatic disease detected by nested RT-PCR." (PMID 25667918, 2014). "In humans, tyrosinase is involved in the pigmentation in melanocytes, as a marker in melanoma patients and as a target for the activation of prodrugs." (PMID 25197562, 2014). "A recent paper proposed targeting of tyrosinase (MITF transcriptional target) by first inducing expression of MITF in melanoma cells using the well-known anti-folate drug methotrexate." (PMID 24743024, 2014). "Tyrosinase has been isolated from bovine eyes and melanoma cells, and the full-length human tyrosinase gene cloned." (PMID 24392141, 2014). "Our results also confirmed that DSU and SAB can suppress melanin production in α-MSH-stimulated B16 melanoma cells through the inhibition of tyrosinase activity." (PMID 24531218, 2014). "After methotrexate-mediated upregulation of MITF in melanoma cells, tyrosinase expression was induced." (PMID 25538895, 2014). "In this study, we analyzed the effects of CGA on cell proliferation, melanin content and tyrosinase of B16 murine melanoma cells." (PMID 25157464, 2014). "The induction of canine melanoma cell differentiation by lupeol was confirmed by evaluating some differentiation markers such as tyrosinase with real-time RT-PCR." (PMID 25392802, 2014). "On the contrary, Fb-a and Fb-b increased tyrosinase activities as well as melanin content in B16 melanoma cells." (PMID 25197307, 2014). "Tyrosinase is used as a potential prodrug for treating melanoma where patients were successfully treated via tyrosinase activity." (PMID 24895537, 2014). "For example, a serial analysis of two melanoma-associated markers (tyrosinase and MART-1) was shown to be an independent predictor of disease recurrence for stage IV melanoma patients after surgery and adjuvant therapy." (PMID 24743024, 2014). "For the case of melanoma, tissue specific promoters have been described, and these include tyrosinase and melanoma inhibitory activity (MIA)." (PMID 23634303, 2013). "Methanol extract of Eupatorium triplinerve Vahl demonstrated inhibitory activities on melanin formation in B16 melanoma cells and tyrosinase enzyme activity." (PMID 23431351, 2013). "First, we have investigated influence of fluvastatin on tyrosinase protein synthesis during melanogenesis enhanced by UVB irradiation of B16F10 melanoma cell line." (PMID 23846727, 2013). "Cellular melanin content and tyrosinase activity in murine B16F10 melanoma cells were determined after α-MSH stimulation with or without pre-treatment of SHT at the concentration of 250 and 500 μg/ml." (PMID 23981281, 2013). "We have recently developed a new melanoma vaccine clinical trial testing immunization with three full length melanoma tumor antigens (HAdV-5 TMM2, encoding Tyrosinase, MART-1 and MAGE-A6), instead of a single antigen, as in our previous trial." (PMID 24829755, 2013). "Raspberry ketone from Rheum officinale inhibits melanogenesis through a posttranscriptional regulation of tyrosinase gene expression in cultured B16 melanoma cells." (PMID 23431351, 2013). "Melanin is produced in melanocytes and melanomas through metabolism of melanogenic enzymes, such as tyrosinase." (PMID 23762150, 2013). "The melanogenesis inhibition of norartocarpetin was determined by cellular melanin content and tyrosinase in B16F10 melanoma cell." (PMID 24325567, 2013).
melanoma (continued). "Tyrosinase inhibition serves as crucial strategy to treat skin disorders like hyperpigmentation and melanoma." (PMID 23666006, 2013). "The expression of tyrosinase in B16F10 melanoma cell line, after induction of melanogenesis by UVB irradiation, was examined by Western blot analysis." (PMID 23846727, 2013). "Our observations indicated that CC-EO and cinnamaldehyde inhibited α-MSH-induced melanogenesis through the tyrosinase inactivation and the simultaneous suppression of oxidative stress in B16 melanoma cells." (PMID 24051402, 2013). "One potential target for a vaccine strategy is tyrosinase (Tyr), a prototypical melanocytic differentiation antigen that is expressed homogenously by most melanoma specimens and which elicits spontaneous CD8+ T cell responses." (PMID 24829756, 2013). "Our finding was the first demonstration that the quinone-protein adduct formation actually takes place in melanoma cells and melanoma tissues through the tyrosinase-mediated mechanism." (PMID 23533767, 2013). "It is well known that the clinically “amelanotic” melanoma tissues always have tyrosinase activity to some extent, and that “in vitro amelanotic” melanoma cells become “melanotic” ones when they are regrown in the in vivo condition." (PMID 23533767, 2013). "The drug further augmented the processing and shedding of melanocyte differentiation antigens by inducing melanosome autophagy and enhanced tyrosinase ubiquitination, ultimately activating dendritic cells, which induced cytotoxic melanoma-reactive cells." (PMID 23533767, 2013). "Curcumin and its analogs have shown decreased melanin production and tyrosinase inhibition, thus acting as potential anti-melanoma drugs leads." (PMID 23666006, 2013). "According to the potent melanoma immunotherapy theory using monobenzone, tyrosinase appears to trigger melanoma regression." (PMID 23533767, 2013). "The recent report showed that gallic acid suppressed melanogenesis in melanoma cells through inhibition of tyrosinase, TRP-1, Dct, and MITF." (PMID 24129178, 2013). "Human leukocyte antigen (HLA)-A1, A2, A24 or B35 stage IIb-IV melanoma patients received up to five doses of the mouse tyrosinase DNA vaccine by EP every three weeks at dose levels of 0.2 mg, 0.5 mg, or 1.5 mg per injection." (PMID 24829756, 2013). "SOX9 and SOX10, overexpressed in melanomas, are implicated in the regulation of genes involved in melanogenesis such as MITF and tyrosinase." (PMID 24086527, 2013). "Of these, the shared antigens, such as tyrosinase and melan-A in the case of melanoma, are well-defined and have broad specificity for melanoma patients." (PMID 22438914, 2012). "In our study we proved that DMSO induces melanogenesis in A-375 cell line, thereby it stimulates the differentiation of melanoma cells and increases the activity of tyrosinase enzyme." (PMID 22654640, 2012). "Here, CTCs were enriched (∼400X) from blood of melanoma patients using a simple centrifugation device (OncoQuick), and 4 melanocyte target RNAs (TYR, MLANA, MITF, and MIF) were quantified using QPCR." (PMID 22829910, 2012). "Among these identified pathways, the N-glycan pathway has been shown to be involved in tyrosinase and melanin synthesis in melanoma cells as well as melanoma cell metastasis." (PMID 23056502, 2012). "Western blotting analysis showed that the NVs and exosomes contained similar levels of melanoma antigens, such as tyrosinase and melan-A." (PMID 22438914, 2012). "To examine the action mechanism of the inhibitory effect of M. grandiflora L. flower extract on melanogenesis more precisely, we assessed intracellular tyrosinase activity in B16F10 melanoma cells." (PMID 22672352, 2012). "Geoditin A at sublethal doses (≤5 μg/mL) decreased melanogenesis and glycosylation of tyrosinase (TYR) in murine B16 melanoma cells in a dose-dependent, but ROS- and MITF-independent manner." (PMID 22412813, 2012).
melanoma (continued). "Tyrosinase derived peptides are presented at the surface of the melanoma cells and recognized by the infiltrating cytotoxic T lymphocytes." (PMID 22905195, 2012). "Melanoma cells are malignant tumor cells of melanocytes, expressing mainly the rate-limiting enzyme TYR involved in the biosynthesis of melanin." (PMID 23028833, 2012). "ELISA test showed significantly (p < 0.0000004 and p < 0.04) lower levels of IgM anti-tyrosinase autoantibodies, in melanoma and vitiligo patients respectively, compared to controls." (PMID 22834951, 2012). "The question arises are some other sources of melanoma-associated antigens e.g. melanin or the key molecule in its biosynthesis - tyrosinase (from edible mushrooms), immunogenic in melanoma patients, in people with vitiligo, and in healthy people?" (PMID 22834951, 2012). "Homoisoflavanone, sappanone A, was isolated from Caesalpinia sappan and proven to dose-dependently inhibit both melanogenesis and cellular tyrosinase activity via repressing tyrosinase gene expression in mouse B16 melanoma cells." (PMID 22949866, 2012). "Here, we investigate the role of EDEM1 in the processing of tyrosinase, a tumour antigen overexpressed in melanoma cells." (PMID 22905195, 2012). "50% of melanoma patients have tumour-infiltrating lymphocytes (TILs) recognising tyrosinase and Melan A, indicating that these antigens are important in the natural melanoma immunosurveillance." (PMID 22506061, 2012). "Tyrosinase is constitutively expressed in melanocytes and overexpressed in melanoma cells as a transmembrane glycoprotein with two copper binding domains required for its oxido-reductase activity." (PMID 22905195, 2012). "No change in mobility was observed for the Δ5 mutant expressed either in HEK cells or in the A375 melanoma cells suggesting that this sequon is rarely occupied in human tyrosinase." (PMID 21625599, 2011). "Tumor-specific unique antigens encompass melanocyte/melanoma differentiation antigens, such as tyrosinase, MART1 and gp100, prostate-specific antigen (PSA) and Idiotype (Id) antibodies." (PMID 21211062, 2011). "This study demonstrated that RK from R. officinale inhibited melanogenesis through a post-transcriptional regulation of tyrosinase gene expression in cultured B16 melanoma cells." (PMID 21954327, 2011). "For example, on the basis of the successful use of gp100, MART-1/Melan-A, and tyrosinase in melanoma preclinical models, several clinical trials were conducted or are still ongoing." (PMID 24212974, 2011). "The use of cis -regulatory elements based on various combinations of the tyrosinase gene promoter and additional heterologous enhancers, which control transcription for specific transgene expression in melanoma, has been described in a number of studies." (PMID 22649681, 2011). "The construct consisting of the human TYR promoter (209 bp) and two or more sequentially attached human TYR enhancers (200 bp each) exhibit the highest specific effect upon transfection of melanoma cell lines." (PMID 22649681, 2011). "Tyrosinase promoter was used for the expression of HSV-tk or IL-2 for the treatment of malignant melanomas." (PMID 21453283, 2011). "Patients with negative SLN by standard histopathology and immunohistochemistry underwent molecular staging by reverse transcriptase polymerase chain reaction (RT-PCR) to detect melanoma-specific mRNA (tyrosinase, MART 1, MAGE 3, gp100)." (PMID 22220281, 2011). "Recent GWAS have unveiled association between SNPs or genetic variants in MC1R, TPCN2, ASIP, KITLG, SLC24A5, TYR, IRF4, OCA2/HERC2, SLC24A4, SLC45A2, TYRP1, and pigmentation as well as melanoma." (PMID 21559390, 2011). "Quercetin, for example, is a naturally occurring polyphenol that becomes activated in tyrosinase expressing cells such as melanoma." (PMID 20540768, 2010). "Therapy with xenogeneic tyrosinase DNA vaccines was used in phase I trials of spontaneous advanced malignant melanoma in dogs, a disease very similar to human melanoma." (PMID 21197271, 2010).
melanoma (continued). "Cytokine production (IFN-γ, IL-10) by TyrTCR-transduced cells was also detected following co-culture with a melanoma tumor cell line expressing tyrosinase naturally processed and presented in the context of HLA-A*0201 (data not shown)." (PMID 20668510, 2010). "Tyrosinase expression in melanoma tissue also provides the possibility of local treatment of cutaneous metastasis with the MIC regimen." (PMID 20498710, 2010). "The C57BL/6 (H2b) melanoma cell line B16 is indeed slightly immunogenic and as a pigmented cell line, extremely sensible to the effect of anti-tyrosinase antibodies." (PMID 20672001, 2010). "Given the very attractive ability of VRPs to induce humoral and T cell responses against tyrosinase, we sought to further investigate the potentials of VRP encoding different MDAs as vaccines for melanoma." (PMID 20844763, 2010). "To express de novo TCRs in Tregs, we first generated an expression vector employing a previously characterized tumor-reactive TCR (TyrTCR) that recognizes the melanoma antigen tyrosinase in the context of the MHC class I molecule HLA-A*0201." (PMID 20668510, 2010). "Similar poor results were observed in nineteen patients with stage IV melanoma which were treated with a plasmid encoding T cell epitopes from MART-1 and tyrosinase by intranodal injection." (PMID 21197271, 2010). "To investigate the efficacy of VRPs encoding MDAs as an immunotherapeutic approach for melanoma, we compared VRP encoding the mouse MDAs tyrosinase (tyr), gp100 or TRP-2." (PMID 20844763, 2010). "We have previously shown that alphavirus-based virus-like replicon particles (VRP) simultaneously activate strong cellular and humoral immunity against the weakly immunogenic melanoma differentiation antigen (MDA) tyrosinase." (PMID 20844763, 2010). "Tyrosinase was used as single cDNA vaccine applied in stage II melanoma patients by recombinant modified vaccinia virus Ankara (MVA)." (PMID 21197271, 2010). "High-frequency alleles with small effects on melanoma risk have also been identified in a number of genes, including MC1R (Melanocortin 1 Receptor) and TYR (tyrosinase)." (PMID 21203498, 2010). "Enzymatic activation of Qct by tyrosinase specifically enhances its anti-tumor activity in melanoma cells and increases the effectiveness of additional cytotoxic compounds." (PMID 20540768, 2010). "Weekly stimulations of patients' PBMC with the pDC line pulsed either with MelA, GP100, TYR or MAGE-3 peptide led to the massive amplification of specific CD8+ T cells for at least 2 out of 4 melanoma antigens." (PMID 20454561, 2010). "They include tyrosinase or tyrosinase-related proteins, an unidentified 75 kDa protein obtained from cultured human melanoma cells (G-361), and the S-100 protein." (PMID 20029145, 2010). "The tumors were strongly and diffusely positive for S100 and expressed the melanocyte markers tyrosinase, Dct, Pax3, and silver, consistent with a diagnosis of melanoma." (PMID 20141835, 2010). "In the present study, 8-OHDe was demonstrated to exert potent inhibition in both melanogenesis and cellular tyrosinase activities in mouse B16 melanoma cells, where the IC50 values of the inhibitions by the compound are 10.54 and 6.17 μM, respectively." (PMID 20057943, 2009). "From the results of the study, it was concluded that 8-OHDe, the potent suicide substrate of mushroom tyrosinase, has depigmenting activities in both mouse melanoma cells and in human volunteers." (PMID 20057943, 2009). "Early studies on the stability of tyrosinase revealed that tyrosinase is degraded endogenously in melanoma cells." (PMID 20057953, 2009). "This includes tyrosinase or tyrosinase-related proteins and a 75 kDa protein obtained from cultured human melanoma cells." (PMID 19756183, 2009).